RNU6-494P (RNA, U6 small nuclear 494, pseudogene)
Gene: Small nuclear RNA gene on chromosome 12 (32,477,382 to 32,477,471, reverse strand). Ensembl gene ENSG00000253063.
Homologues: Orthologues: macaque U6 (97% identical), dog U6 (88% identical), guinea pig U6 (77% identical), pig U6 (76% identical). Paralogues in human: RNU6-43P (90% identical), RNU6-939P (90% identical), RNU6-1310P (89% identical), RNU6-422P (89% identical), RNU6-1031P (88% identical), RNU6-1083P (88% identical), RNU6-1091P (88% identical), RNU6-19P (88% identical), RNU6-24P (88% identical), RNU6-434P (88% identical), RNU6-454P (88% identical), RNU6-726P (88% identical), and 1285 more.